RAB40C (RAB40C, member RAS oncogene family)
Description:
RAB40C small GTPase acts as substrate-recognition component of the ECS(RAB40C) E3 ubiquitin ligase complex which mediates the ubiquitination and subsequent proteasomal degradation of target proteins. The Rab40 subfamily belongs to the Rab family that are key regulators of intracellular membrane trafficking, from the formation of transport vesicles to their fusion with membranes. Rabs cycle between an inactive GDP-bound form and an active GTP-bound form that is able to recruit to membranes different sets of downstream effectors directly responsible for vesicle formation, movement, tethering and fusion. As part of the ECS(RAB40C) complex, mediates ANKRD28 ubiquitination and degradation, thereby inhibiting protein phosphatase 6 (PP6) complex activity and focal adhesion assembly during cell migration. Also negatively regulate lipid droplets accumulation in a GTP-dependent manner.
Synonyms: RARL; RASL8C
Tractability: Antibody: UniProt places it where antibodies can reach, with high confidence; its Gene Ontology location is reachable by antibodies, with medium confidence. PROTAC: ubiquitination databases record sites on it; its protein half-life has been measured.
Gene: Protein-coding gene on chromosome 16 (589,007 to 629,273, forward strand). Ensembl gene ENSG00000197562.
Subcellular location: Cell membrane; Cytoplasm, cytosol; Golgi apparatus membrane
Subcellular location (Human Protein Atlas): Vesicles
Pathways (Reactome):
Metabolism of proteins: RAB geranylgeranylation
Gene Ontology:
Molecular function: G protein activity; GTPase activity; protein binding; ubiquitin-like ligase-substrate adaptor activity; GTP binding
Biological process: cell migration; lipid droplet formation; negative regulation of focal adhesion assembly; proteasome-mediated ubiquitin-dependent protein catabolic process; exocytosis; intracellular signal transduction; protein ubiquitination
Cellular component: Cul5-RING ubiquitin ligase complex; cytosol; Golgi apparatus; Golgi membrane; lipid droplet; endosome; plasma membrane; synaptic vesicle
Genetic constraint (gnomAD): Loss-of-function variants: 8 observed, 27.53 expected, observed/expected ratio (o/e) 0.29, 90% interval 0.17 to 0.52. The upper end of that interval is the gene's LOEUF score, 0.52, which puts it in group 2 of 6, group 1 being the genes least tolerant of losing a copy. Missense variants: 288 observed, 403.7 expected, observed/expected ratio (o/e) 0.71, 90% interval 0.65 to 0.79. Synonymous variants: 201 observed, 174.5 expected, observed/expected ratio (o/e) 1.15, 90% interval 1.03 to 1.29.
Homologues: Orthologues: macaque RAB40C (100% identical), mouse Rab40c (99% identical), pig RAB40C (99% identical), guinea pig RAB40C (99% identical), dog RAB40C (99% identical), tropical clawed frog rab40c (96% identical), zebrafish rab40c (95% identical), chimpanzee RAB40C (73% identical). Paralogues in human: RAB40B (79% identical), RAB40A (75% identical), RAB40AL (74% identical), RAB10 (30% identical), RAB8A (30% identical), RAB8B (29% identical), RAB1A (28% identical), RAB1B (28% identical), RAB13 (28% identical), RAB11B (28% identical), RAB3B (27% identical), RAB11A (27% identical), and 56 more.
Diseases named in the same sentence as RAB40C in open-access papers:
RAB40C is named in the same sentence as 12 diseases in open-access papers, as found by Europe PMC text mining. Sharing a sentence is not in itself a finding about the gene and the disease. The quoted sentences say what the papers report.
breast carcinoma (2 papers, 2016 to 2022). "Here, we show that Rab40c regulates the size, location, and number of FAs in breast cancer cells, while also demonstrating that Rab40c interacts with ankyrin repeat domain 28 protein (ANKRD28), which is a scaffolding subunit of heterotrimeric protein phosphatase PP6 complex." (PMID 35512830, 2022). "Importantly, ANKRD28-containing PP6 complex inhibits FA formation, and Rab40c directly regulates ubiquitination and degradation of ANKRD28 in breast cancer cells." (PMID 35512830, 2022). "Rab40b is upregulated in grade 3 breast cancers, but its close homologues Rab40a and Rab40c are not." (PMID 27789576, 2016).
colon cancer (2 papers, 2018 to 2023). "It should be noted that the involvement of RAB40C in gastric cancer has previously been investigated; however, this is the first report in which the enzyme also has a role in colon cancer." (PMID 30112187, 2018). "Similarly, the ubiquitin E3 ligase RAB40C regulates the degradation of RACK1 in colon cancer cell lines." (PMID 37848434, 2023). "In light of this, we were curious as to whether we could replicate this via silencing of RAB40C in a colon cancer cell line." (PMID 30112187, 2018). "We show that silencing of RAB40C results in the upregulation of RACK1, which in turn can reduce proliferation and colony formation of HCT116 colon cancer cells and influence the migration of T cells." (PMID 30112187, 2018).
gastric cancer (2 papers, 2018 to 2023). A primary or metastatic malignant neoplasm involving the stomach. "Rab40C overexpression has been noted in gastric cancer and Lung Squamous Cell Carcinoma, while, in cases of osteosarcoma resulting in death, Rab40C levels are reduced." (PMID 37736498, 2023).
cancer (5 papers, 2018 to 2024). A tumor composed of atypical neoplastic, often pleomorphic cells that invade other tissues. "Among them, CDH1, ETNK2, ADARB2, and RAB40C are found to be aberrantly methylated in different cancers." (PMID 32961999, 2020). "Next, we set out to show that the control of RACK1 levels by RAB40C can have functional consequences in the transformation and proliferation of cancer cells, and in the migration of T cells." (PMID 30112187, 2018). "The linking of Rab40C to a variety of cancer types indicates that dysregulation of Rab40C expression may contribute to cancer metastasis." (PMID 37736498, 2023). "Similarly to Rab40B, Rab40C expression has been analyzed in a variety of cancer types." (PMID 37736498, 2023). "Using siRNA screening, we identified RAB40C as the ubiquitin E3 ligase responsible for ubiquitination of RACK1, and that the action of RAB40C in controlling RACK1 levels is crucial to both cancer cell growth and migration of T cells." (PMID 30112187, 2018). "The E3 ligase RAB40C ubiquitinates and destabilizes RACK1 to promote cancer cell proliferation." (PMID 38315284, 2024). "Thus, although additional studies will be needed to determine the mechanisms of PP6-dependent FAK regulation, our data imply that the Rab40c-ANKRD28/PP6 pathway contributes to regulating FAK activity and FA disassembly during cancer cell migration." (PMID 35512830, 2022).
tumor (4 papers, 2017 to 2025). "When most family members, which act as tumor suppressors, are downregulated, they promote tumor cell proliferation and invasion by activating target genes such as RAB40C and C-Myc, thereby significantly reducing chemosensitivity." (PMID 41425723, 2025). "In MDA‐MB‐231, we found a significant upregulation of LAPTM4B, RAB40C, MMP3, and downregulation of PRKCZ after tumor treatment with doxorubicin." (PMID 34109737, 2022). "Finally, RAB40C protein regulates, via an ubiquitin-proteasome system, the degradation of RACK1 protein, which is important in tumour growth and T-cell migration." (PMID 32707447, 2020).
RAB40C also shares sentences with these, for which no sentence is quoted: Lung Squamous Cell Carcinoma (2 papers); clear cell renal cell carcinoma (1); head and neck squamous cell carcinoma (1); lung adenocarcinoma (1); osteosarcoma (1); pancreatic ductal adenocarcinoma (1); uterine corpus endometrial carcinoma (1).